ENSG00000214546 (novel transcript)
Gene: Long non-coding RNA gene on chromosome 17 (39,617,471 to 39,623,157, forward strand). Ensembl gene ENSG00000214546.
Gene Ontology:
Biological process: SRP-dependent cotranslational protein targeting to membrane, signal sequence recognition
Cellular component: signal recognition particle, endoplasmic reticulum targeting